PHOX2B (paired like homeobox 2B)
Diseases named in the same sentence as PHOX2B in open-access papers (continued):
Sharing a sentence is not in itself a finding about the gene and the disease.
neuroblastoma (continued). "However, only 1–2% of all neuroblastoma cases are familial, and, of these, only about 6–10% can be attributed to PHOX2B mutations." (PMID 34769149, 2021). "In addition, mutations of PHOX2B gene, both somatic and germline, have been reported in previous neuroblastoma studies." (PMID 33468206, 2021). "Previous studies showed that PHOX2B is associated with neuroblastoma." (PMID 33468206, 2021). "Association of PHOX2B rs28647582T>C polymorphism with neuroblastoma risk." (PMID 30799307, 2019). "Though many cancers can be attributed to genetic changes induced by hereditary predisposition, as described in neuroblastoma for the PHOX2B and ALK genes, others may be the result of lifestyle or environmental factors." (PMID 30200332, 2018). "Several mutations in the PHOX2B have been identified in sporadic and familial neuroblastoma." (PMID 28055978, 2017). "However, germline mutations of PHOX2B accounted for merely 6.4 % of hereditary neuroblastoma cases and were rarely detected in more common sporadic cases of the disease, indicating that the gene was not the major pathogenic gene." (PMID 28055978, 2017). "A similar loss of differentiation was observed upon overexpression of a neuroblastoma-linked truncation mutation (K155X) and a frameshift mutation (676delG) in the presence of endogenous phox2b, indicating that these variants function in a dominant-negative manner." (PMID 23754957, 2013). "Mutations in PHOX2B have been found in a minority of familial neuroblastoma cases." (PMID 20398431, 2010). "However, it is not known if the reciprocal could occur with ALK signaling affecting PHOX2B levels and thereby also cause perturbation of neuronal differentiation during specific developmental windows and give rise to neuroblastoma and a CCHS-like condition." (PMID 36140661, 2022). "Additionally, PHOX2B mutations also occur in about 2% of sporadic cases of neuroblastoma." (PMID 30200332, 2018). "In addition to rare heterozygous PHOX2B mutations detected in neuroblastoma, the pathogenetic role of this gene in neuroblastoma is also indicated by its anomalous overexpression in tumor samples and cell lines, which correlates with the excessive expression of its transcriptional target ALK." (PMID 29069774, 2017). "However, very recent data suggest that PHOX2B overexpression is likely pathogenic in the earliest steps of neuroblastoma growth, associated with poor neuroblast differentiation and expansion, while in the final metastatic phase it seems to protect against aggressive migration capability." (PMID 29069774, 2017). "Indeed, heterozygous mutations of the PHOX2B coding region were identified in sporadic and familial cases of isolated or syndromic neuroblastoma, a tumor associated with other neurocristopathies such as congenital central hypoventilation syndrome and Hirschsprung disease." (PMID 29069774, 2017). "Sympathetic neural cells derived from chick and mouse embryos transfected with gain-of-function PHOX2B variants seen in neuroblastoma demonstrated significantly more cell proliferation than wild-type PHOX2B, indicating that wild-type PHOX2B may act a tumor suppressor." (PMID 26771642, 2016). "Both PHOX2B and Alk mutations may increase and prolong proliferation of embryonic sympathetic neurones in mouse models, increasing the probability of additional mutations within this cell lineage, leading to the clinical manifestation of neuroblastoma." (PMID 25928806, 2014). "Thus, PHOX2B deficiency due to whole-allele deletion should be considered another mechanism whereby individuals might acquire a predisposition to neuroblastoma." (PMID 23754957, 2013). "Furthermore, since both frameshift and truncation changes in the PHOX2B gene appear to generate stable proteins that lack the transactivation potential of WT PHOX2B, their contribution to neuroblastoma predisposition could be twofold." (PMID 23754957, 2013).
neuroblastoma (continued). "To determine whether phox2b loss might obviate the induction of differentiation by RA, we treated control and phox2b MO embryos with various concentrations of 13-cis-retinoic acid, which is commonly used in the treatment of patients with neuroblastoma." (PMID 23754957, 2013). "TESLA-seq was applied across a genomic region surrounding the PHOX2B gene, a key transcription factor affecting the growth of neuroblastoma cells, to reveal 60 regulators for 30 genes." (PMID 40930101, 2025). "Our initial efforts focused on neuroblastoma, where we targeted the developmental transcription factor and master regulator in neuroblastoma tumor maintenance PHOX2B." (PMID 40672284, 2025). "We calculated automated H-scores (a quantitative measure of staining intensity) for pSMAD1/5/9 in PHOX2B positive neuroblastoma cells in bulk tumors, invasive regions, and disseminated single cancer cells in the bone marrow." (PMID 40021625, 2025). "In summary, using CRISPRa screening in a neuroblastoma cell line in the 2 Mb genomic space on chromosome 4 surrounding the PHOX2B gene, we have identified 619 CaREs that play a role in cellular growth or survival." (PMID 40930101, 2025). "The neuroblastoma tumouroids demonstrated diffuse strong nuclear PHOX2B staining, Ewing sarcoma tumouroids showed circumferential membrane staining for CD99, and osteosarcoma tumouroids with nuclear SATB2 staining." (PMID 41034452, 2025). "Mycophenolate mofetil and XAV939 are two molecules that have demonstrated potential to inhibit PHOX2B in neuroblastoma cells in preclinical studies." (PMID 40104501, 2025). "Markers of SA cells have been found to be highly expressed in neuroblastoma tumors and constitute the core regulatory circuitry in the adrenergic subtype of neuroblastoma, including PHOX2B, HAND2 and GATA310,11." (PMID 39367051, 2024). "PHOX2B, as a validated neuroblastoma-specific gene, was assigned an extremely low BayesTS score (0.03), consistent with the preclinical safety testing of this therapy and supporting the capacity of BayesTS to prioritize valid cancer targets." (PMID 39515334, 2024). "We confirmed that the commonly used neuroblastoma MRD markers (including PHOX2B, TH, CHRNA3, GAP43) are rarely expressed in mesenchymal neuroblastoma cell lines." (PMID 39722049, 2024). "As a result, the crucial role of PHOX2B in sympathetic ganglia formation can be used to outline the basics of neuroblastoma pathogenesis." (PMID 38673496, 2024). "The goal of this scope review is to shed light onto overlooked signaling pathways possibly involved in the carcinogenesis of neuroblastoma, with emphasis on Nrf2, NF-κB, and Phox2B." (PMID 38666930, 2024). "Histologically, expression of the neuroblastoma marker PHOX2B was variable across each protocol with Protocol #4 derived tumors expressing the most PHOX2B." (PMID 39367051, 2024). "A recently reported peptide-centric CAR strategy targets the intracellular oncogenes PHOX2B that can generate a self-antigen (QYNPIRTTF) presented on multiple HLA-I alleles, rendering it a promising cancer target in a wide range of neuroblastoma patients." (PMID 39515334, 2024). "Based on our findings, Protocol #4 is the most reliable at generating SA cells and neuroblastoma tumors with expression of PHOX2B." (PMID 39367051, 2024). "This review outlines the molecular and functional biology of the three transcription factors Nrf2, NF-κB and Phox2B, insinuating the role of their interaction in the development, progression and aggressive behaviour of neuroblastoma." (PMID 38666930, 2024). "Among the many transcription factors involved at different neuroblastoma differentiation stages, PHOX2B and MYCN with their transcriptional targets ALK and LIN28B, and the tumor suppressor miRNAs let-7, miR-34, and miR-204 are mainly involved." (PMID 38666930, 2024). "This review highlights the abnormal regulation of NF-κB, Nrf2, and Phox2B as well as their interactions among each other in neuroblastoma." (PMID 38666930, 2024).
neuroblastoma (continued). "As a positive control, we also assessed the expression of Ngfr and Phox2b, two genes known to be highly expressed in neuroblastoma." (PMID 38095019, 2023). "The mRNA content was determined using several multiplex droplet digital PCR (ddPCR) assays for a neuroblastoma-specific gene panel (PHOX2B, TH, CHRNA3) and a cell cycle regulation panel (E2F1, CDC6, ATAD2, H2AFZ, MCM2, DHFR)." (PMID 37046768, 2023). "Pathology was consistent with human neuroblastoma, showing small round blue cell tumors with Homer-Wright rosettes, high mitoses and karyorrhectic index, and strong PHOX2B staining." (PMID 37980388, 2023). "To study cfRNA in limited volume samples of pediatric patients with neuroblastoma, we first designed and optimized a multiplex ddPCR which included the neuroblastoma-specific targets PHOX2B, CHRNA3 and TH, and GUSB as a reference gene." (PMID 37046768, 2023). "Inspection of tumors indicated neuroblastoma characteristic small round blue tumor cell morphology and elevated nuclear Phox2b protein." (PMID 37246217, 2023). "RT-qPCR of BM and PB samples at diagnosis showed detection of all neuroblastoma mRNA-markers, including the neuroblastoma-specific marker PHOX2B." (PMID 37664065, 2023). "Peptide-centric chimeric antigen receptors (PC-CARs) provide a platform to address the challenges involved in targeting intracellular oncoproteins, and PC-CARs based on the neuroblastoma-dependency gene PHOX2B induce elimination of aggressive tumors." (PMID 37938771, 2023). "The presence of neuroblastoma-specific mRNA in the cellular compartment of blood and bone marrow, such as PHOX2B, TH and CHRNA3, has been shown to correlate with outcome, enabling response monitoring in patients with high-risk disease." (PMID 37046768, 2023). "Taken together, we suggest that PHOX2B is a highly specific tumour antigen in neuroblastoma and an ideal candidate for therapeutic targeting." (PMID 37938771, 2023). "Here we present the discovery of recurring lineage-restricted oncoproteins presented on MHC, focusing on immunotherapeutic targeting of the neuroblastoma CRC master regulator PHOX2B using PC-CARs." (PMID 37938771, 2023). "We focus on the known history of associations between HSCR and CCHS, in addition to recently found genetic mutations in paired-like homeobox 2B that link HSCR, CCHS, and neuroblastoma." (PMID 36466361, 2022). "One study indicated that PHOX2B directly regulates ALK transcription, thereby providing a direct link between these two neuroblastoma predisposition genes." (PMID 36140661, 2022). "Large cells measuring 14-16 μm were captured, which expressed known neuroblastoma markers GD2 synthase, PHOX2B and TH – the primers having been first verified by demonstrating their expression in 7 neuroblastoma cell lines." (PMID 36176417, 2022). "Recently, the heterogeneity of neuroblastoma cells was defined by super-enhancer-associated transcription factors, such as MYCN and PHOX2B, and different tumor-cell subpopulations showed different characteristics of tumor development and metastasis." (PMID 35884407, 2022). "In agreement with the previous findings of both studies, none of the examined CNS tumor cases in our study showed the pattern of widespread nuclear PHOX2B immunoreactivity that would be expected in a peripheral neuroblastoma." (PMID 35763016, 2022). "Using this method, we identified an increased number of PHOX2B+VIM+ double-positive neuroblastoma cells after brequinar treatment and at relapse." (PMID 35943801, 2022). "A previous study demonstrated that high expression levels of PHOX2B promoted the growth of human neuroblastoma cells in xenograft model." (PMID 35197367, 2022). "Overall, none of the CNS tumors in our study demonstrated diffuse strong nuclear expression of PHOX2B comparable to that expected in the setting of peripheral neuroblastoma." (PMID 35763016, 2022).
neuroblastoma (continued). "Since PHOX2B and TH showed the highest relative expression across the panel of cell lines compared to non-neuroblastoma cell line AGS, the separation method and primers were then used to discriminate neuroblastoma from blood cells in clinical samples." (PMID 36176417, 2022). "All 16 peripheral neuroblastomas, including eight cases with intracranial metastasis, showed widespread nuclear staining for PHOX2B, with overall percent positivity ranging from 1.8% to 79.2%." (PMID 35763016, 2022). "Attempts to enrich neuroblastoma CTCs have been largely limited to capture-based methods relying on cellular expression of TH, PHOX2B, NCAM and GD2 synthase, though these inherently introduce a selection bias." (PMID 36176417, 2022). "Precise detection of PD-L1+ cells in neuroblastoma tissues must be done by multiplex IHC assay, in which nuclear PHOX2B staining identifies neuroblastoma cells, and PD-L1+ cells are visualized by cell membrane staining by the corresponding antibody." (PMID 35525858, 2022). "In human neuroblastoma cell lines, retinoic acid administration induces cellular differentiation, which is accompanied by a decrease in PHOX2B expression, and in mouse models, a downregulation of PHOX2B inhibits neoplastic proliferation." (PMID 35763016, 2022). "Paired‐like homeobox 2b (PHOX2B) is an established immunomarker for peripheral neuroblastoma and autonomic nervous system cells." (PMID 35763016, 2022). "In about 4% of spontaneous neuroblastoma cases, loss-of-function mutations in PHOX2B (paired-like homeobox 2B) can occur." (PMID 36185250, 2022). "The NB5 assay uses RT-PCR to detect the co-expression of five mRNAs from the neuroblastoma-associated genes, CHGA, DCX, DDC, PHOX2B, and TH." (PMID 34055604, 2021). "Already more than a decade ago, the importance of PHOX2b and Delta-Notch pathway has been observed in a number of familial neuroblastoma." (PMID 34757495, 2021). "Neuroblastoma is the solid extra-cranial tumor associated with genetic defects in transcriptional factors MYCN, ALK, and PHOX2B, which play important role in sympatho-adrenal lineage development." (PMID 32748156, 2021). "S5A), in particular, the two most common neuroblastoma predisposition genes, ALK and PHOX2B, and the cancer gene MYCN, somatic amplification of which is a key adverse marker used clinically for neuroblastoma risk stratification." (PMID 33547074, 2021). "Clinically, immunohistochemical staining of PHOX2B protein is a sensitive and specific marker for undifferentiated neuroblastoma." (PMID 33468206, 2021). "suggests that Phox2b+ hyperplastic cells are halted at the progenitor stage and that Phox2b+ neuronal progenitors are the main cellular target of N-myc in driving neuroblastoma expansion from hyperplasia to tumors." (PMID 33585251, 2020). "PHOX2B expression was reported as reduced in neuroblastoma cells as a result of small molecule combination, which included curcumin, SAHA, and trichostatin." (PMID 33402862, 2020). "The cells express neuroblastoma specific genes such as paired-Phox2b, Dbh, Th, and high levels of N-myc compared to normal tissue." (PMID 33585251, 2020). "Transcription factor ChIP-seq in MYCN-expressing cells confirmed that four of the enhancers (e1, e2, e4, and e5) were bound by each of three noradrenergic neuroblastoma core regulatory circuit transcription factors (PHOX2B, HAND2, GATA3)." (PMID 33199677, 2020). "High levels of DCX, PHOX2B, or TH mRNAs in BM and PB samples at diagnosis or BM samples after induction therapy predicted poor outcome in children with stage 4 neuroblastoma." (PMID 31214500, 2019). "Our aim was to evaluate to what extent several of these well-established driver genes (MYCN, ALK) and neuroblastoma identity genes (PHOX2B) impact lincRNA expression." (PMID 30952905, 2019). "This analysis revealed strong associations between the neuroblastoma lincRNAs MIAT and MEG3 and MYCN and PHOX2B activity or expression." (PMID 30952905, 2019).
neuroblastoma (continued). "A set of six markers (CCND1, DDC, GABRB3, ISL1, KIF1A, PHOX2B) was identified by genome-wide gene expression microarray analyses of 48 neuroblastoma tumors and nine remission BM samples followed by selecting genes with higher tumor-to-BM expression ratios." (PMID 31214500, 2019). "PHOX2B immunohistochemistry confirmed that the obtained tumors were neuroblastomas from the injected CLB-MA BM cell line." (PMID 31452835, 2019). "Elimination of the interaction by HPCAL1 knockdown with small hairpin RNA (shRNA) in the neuroblastoma cells with PHOX2B expression reduced the outgrowth of neurites." (PMID 30843345, 2019). "A set of three markers (DCX, PHOX2B, TH) was identified by genome-wide gene expression microarray analyses of 32 neuroblastoma tumors and pooled PB sample from 24 healthy volunteers followed by selecting genes not expressed in pooled PB samples." (PMID 31214500, 2019). "PHOX2B was first identified as a driver of these developmental disorders, and later identified in neuroblastoma patients with a family history of neuroblastic tumors or congenital malformations." (PMID 30200332, 2018). "In the field of SRBCT and the overlap of nephroblastoma and neuroblastoma two recent reports propose immunohistochemical markers, cyclin D1 and PHOX2B, to be reliable for distinction of neuroblastoma from other malignancies." (PMID 28818093, 2017). "Finally, we wondered whether PHOX2B protein decrease consequent to CQ and MMF treatment could result in down-regulation of Anaplastic Lymphoma Kinase (ALK) gene expression, whose transcription is PHOX2B-dependent and overexpression is considered pathogenic in neuroblastoma." (PMID 29069774, 2017). "Mutations in PHOX2B and RAS pathway genes were previously reported in 2.3% and 3.7% of neuroblastoma cases, but such mutations were less frequent in our screen here." (PMID 29296183, 2017). "DNA Ligase III, Ligase I, and PARP1 silencing significantly decreased neuroblastoma markers expression (TH, Phox2b, and TRKB)." (PMID 29238067, 2017). "PHOX2B overexpression is considered a prognostic marker for neuroblastoma and it is also used by clinicians to monitor minimal residual disease." (PMID 29069774, 2017). "High PHOX2B mRNA levels are therefore considered a sensitive prognostic marker for neuroblastoma since, at diagnosis, they identify children with ultrahigh-risk disease." (PMID 29069774, 2017). "The knockdown of PHOX2B in human neuroblastoma micrometastatic cells proved to increase with tumorigenic and metastatic potential." (PMID 29069774, 2017). "The predominant cells in both hyperplastic lesions and in neuroblastoma samples are largely represented by Phox2B+ progenitors, whose number correlates with tumor growth, which suggests a PHOX2B role also in tumor progression." (PMID 29069774, 2017). "The PHOX2B-mediated downregulation induced an upregulation of TH, a marker for bad prognosis in neuroblastoma." (PMID 26840262, 2016). "In this study we asked if PHOX2B is involved in shaping the malignant and metastatic phenotype of neuroblastoma cells." (PMID 26840262, 2016). "If expression levels of PHOX2B are indeed related to the malignant phenotype of neuroblastoma cells, it is to be expected that knockdown of PHOX2B would promote the malignant properties of these cells." (PMID 26840262, 2016). "DNA hyper-methylation is an epigenetic event occurring in many cancer types and one that plays a role in PHOX2B silencing in neuroblastoma cell-lines and tumors." (PMID 26840262, 2016). "These pre-clinical data strongly suggest that PHOX2B functions as a suppressor of neuroblastoma progression." (PMID 26840262, 2016). "More importantly, this indicates that PHOX2B is a regulator of neuroblastoma progression and metastasis." (PMID 26840262, 2016).